TLR1 (toll like receptor 1)
Description:
Participates in the innate immune response to microbial agents. Specifically recognizes diacylated and triacylated lipopeptides. Cooperates with TLR2 to mediate the innate immune response to bacterial lipoproteins or lipopeptides. Forms the activation cluster TLR2:TLR1:CD14 in response to triacylated lipopeptides, this cluster triggers signaling from the cell surface and subsequently is targeted to the Golgi in a lipid-raft dependent pathway. Acts via MYD88 and TRAF6, leading to NF-kappa-B activation, cytokine secretion and the inflammatory response.
Synonyms: TIL; CD281; KIAA0012; rsc786; TIL. LPRS5
Tractability: Small molecule: a structure with a bound ligand is known; a high-quality ligand is known; it has a binding pocket of medium quality. Antibody: UniProt places it where antibodies can reach, with high confidence; its Gene Ontology location is reachable by antibodies, with high confidence; UniProt predicts a signal peptide or a membrane-spanning region. PROTAC: ubiquitination databases record sites on it; its protein half-life has been measured; a small molecule that binds it is known.
Target class: Enzyme; Hydrolase
Gene: Protein-coding gene on chromosome 4 (38,787,555 to 38,856,817, reverse strand). Ensembl gene ENSG00000174125.
Subcellular location: Cell membrane; Cytoplasmic vesicle, phagosome membrane; Membrane raft; Golgi apparatus
Pathways (Reactome):
Immune System: Beta defensins; ER-Phagosome pathway; MyD88:MAL(TIRAP) cascade initiated on plasma membrane; Regulation of TLR by endogenous ligand; Toll Like Receptor TLR1:TLR2 Cascade
Disease: IRAK4 deficiency (TLR2/4); MyD88 deficiency (TLR2/4); SARS-CoV-2 activates/modulates innate and adaptive immune responses
Gene Ontology:
Molecular function: identical protein binding; lipopolysaccharide immune receptor activity; protein binding; Toll-like receptor 2 binding; lipopeptide binding; signaling receptor activity; transmembrane signaling receptor activity
Biological process: cellular response to triacyl bacterial lipopeptide; detection of triacyl bacterial lipopeptide; positive regulation of interleukin-8 production; positive regulation of toll-like receptor 2 signaling pathway; toll-like receptor signaling pathway; toll-like receptor TLR1:TLR2 signaling pathway; inflammatory response; innate immune response; macrophage activation; positive regulation of interleukin-6 production; positive regulation of tumor necrosis factor production; immune response; lipopolysaccharide-mediated signaling pathway; microglial cell activation; response to bacterial lipoprotein; signal transduction
Cellular component: Golgi apparatus; membrane raft; plasma membrane; plasma membrane raft; receptor complex; Toll-like receptor 1-Toll-like receptor 2 protein complex; membrane; phagocytic vesicle membrane
Genetic constraint (gnomAD): Loss-of-function variants: 30 observed, 30.18 expected, observed/expected ratio (o/e) 0.99, 90% interval 0.74 to 1.35. The upper end of that interval is the gene's LOEUF score, 1.35, which puts it in group 5 of 6, group 1 being the genes least tolerant of losing a copy. Missense variants: 921 observed, 950.63 expected, observed/expected ratio (o/e) 0.97, 90% interval 0.92 to 1.02. Synonymous variants: 320 observed, 349.04 expected, observed/expected ratio (o/e) 0.92, 90% interval 0.84 to 1.01.
Homologues: Orthologues: macaque TLR1 (95% identical), pig TLR1 (79% identical), dog TLR1 (77% identical), guinea pig TLR1 (75% identical), rabbit TLR1 (75% identical), mouse Tlr1 (74% identical), rat Tlr1 (73% identical). Paralogues in human: TLR6 (69% identical), TLR10 (49% identical), TLR2 (28% identical), TLR3 (22% identical), TLR7 (22% identical), TLR8 (22% identical), TLR4 (19% identical), TLR5 (19% identical), LRRC32 (16% identical), CD180 (15% identical), RXFP2 (14% identical), NRROS (14% identical), and 10 more.
Diseases named in the same sentence as TLR1 in open-access papers:
TLR1 is named in the same sentence as 243 diseases in open-access papers, as found by Europe PMC text mining. Sharing a sentence is not in itself a finding about the gene and the disease. The quoted sentences say what the papers report.
leprosy (38 papers, 2007 to 2025). Leprosy is a chronic infectious disease affecting primarily the skin and peripheral nervous system. "A study in Brazil found that polymorphisms in the TLR1 gene were associated with greater protection against leprosy in females." (PMID 38343694, 2024). "It has been shown that while TLR2 SNP was associated with increased risk for leprosy, TLR1 and TLR4 SNP were associated with differential production with chemokine and cytokines." (PMID 37187734, 2023). "Certain studies have suggested that mutations in the TLR1 gene, which change the amount of IL-10 and tumor necrosis factor in macrophages, raise the risk of leprosy in Brazil and India." (PMID 38481606, 2023). "Several single-nucleotide polymorphisms (SNPs) in TLR1 have been recognized to be associated with susceptibility or resistance to leprosy and leprosy reactions." (PMID 35846773, 2022). "Based on our findings, and in accordance with previous studies, we point to the TLR1 (rs5743618) polymorphism as an interesting SNP to be further investigated in its possible role in modulating the immune response in leprosy." (PMID 36313452, 2022). "Examples are, for instance, the acquisition and fast evolution of the APOBEC3G gene in primates, and the dominance of a dysfunctional Toll-like receptor 1 variant associated with protection against leprosy in people of European descent." (PMID 36547255, 2022). "Specifically, the homozygous 602S genotype was associated with a significant reduction in leprosy incidence (odds ratio of 0.48), suggesting that reduced TLR1 surface expression and function is protective against symptomatic leprosy." (PMID 34199501, 2021). "For instance, the human TLR1 602S variant is associated with disrupted cell surface localization of the receptor but is protective against pathology associated with leprosy." (PMID 32096861, 2020). "TLR1 in particular is expressed at higher levels than other TLRs and has been associated with infectious diseases that affect the skin, including Leprosy and Lyme Disease." (PMID 33324666, 2020). "In a CGAS, functionally relevant coding single-nucleotide polymorphisms (SNPs) of TLR1/TLR2 were studied in 543 Bangladeshi leprosy patients and 842 healthy controls, and the polymorphism N248S was found to be associated with leprosy." (PMID 32373110, 2020). "The present study is a pioneer in pointing out the protection to leprosy conferred by the C allele of the TLR1 gene in the female sex, evidenced by the statistically significant association." (PMID 30289892, 2018). "Another transmembrane domain polymorphism in TLR1 (T1805G) was associated with susceptibility to leprosy, regulating the innate immune response." (PMID 29643852, 2018). "The I602S variant in the Toll-like receptor 1 (TLR1) gene was shown to be associated with a decreased leprosy incidence in Turkey." (PMID 30289892, 2018). "Our findings suggest that the TLR1 polymorphism was associated with an increased protection from leprosy in women." (PMID 30289892, 2018). "A scientific study conducted in Minas Gerais, Brazil showed that the variant rs4833095 in the TLR1 gene is a protective factor for leprosy." (PMID 30289892, 2018). "Cytokine and chemokine profiles in leprosy patients according to differentgenotypes of TLR1 SNPs - There were differences in the serum levels of somecytokines and chemokines regarding the TLR1 polymorphisms." (PMID 28327786, 2017). "In populations of Brazil, case–control and family studies have been performed with 3,162 individuals showing an association between TLR1 248S and leprosy; corroborating the finding that 248S is a susceptibility factor for leprosy." (PMID 26793196, 2015). "Conversely, the TLR1 602S allele was significantly underrepresented amongst leprosy patients, with an odds ratio for infection of 0.48 (P < 0.05) among TLR1 602S/S homozygotes." (PMID 22529866, 2012).
leprosy (continued). "It is of interest to note that the geographic distribution of the TLR1 602I allele, which increases susceptibility to M. leprae by 1.5 times, is highest in regions where leprosy is most endemic." (PMID 22529866, 2012). "Firstly, this present study is the first to show the consistent effect of TLR1 on leprosy susceptibility, at a significance level exceeding a genome-wide threshold." (PMID 20617178, 2010). "More recently, we and others discovered that SNP TLR1_T1805G is associated with deficient TLR1 signaling as well as susceptibility to leprosy and leprosy reversal reaction." (PMID 19543401, 2009). "Interestingly, TLR1 N248S was previously shown to be associated with increased susceptibility to different infectious diseases including cSSSIs, tuberculosis, leprosy, aspergillosis, candidemia, Q fever, and malaria." (PMID 31786695, 2020). "Previous studies showed that TLR1 variants N248S is a susceptibility factor for leprosy." (PMID 29643852, 2018). "The group analyzed 933 Nepalese leprosy patients, 238 of whom with reversal reaction, and investigated the association of TLR1 variation with different clinical forms of leprosy or reversal reaction, demonstrating that the1805G allele is associated with protection from reversal reaction." (PMID 29643852, 2018). "New studies that include other polymorphisms, such as I602S in the TLR1 gene designated as protector in the populations of Turkey10 and India11, are needed to improve understanding about genetic susceptibility to leprosy as well as the differences in susceptibility between men and women." (PMID 30289892, 2018). "The Toll-like receptor gene cluster, shown to modulate the response to Yersinia pestis and its member TLR1 involved in leprosy susceptibility, were also identified as well as the IFITM3 gene, whose expression was demonstrated to protect against influenza A infection." (PMID 26553317, 2015). "Since associations of the TLR1 SNP A743G and T1805G with higher susceptibility to leprosy, tuberculosis and sepsis have been demonstrated, TLR1 polymorphisms may also have clinical implications for aged subjects." (PMID 23391127, 2013). "However, several disease association studies have revealed a protective role for the deficient TLR1 602S variant against the development of both clinical leprosy and tuberculosis." (PMID 22529866, 2012). "The association between the hypofunctional TLR1 phenotype and protection against leprosy suggests that M. leprae may utilize TLR1 as part of its pathogenic mechanism." (PMID 22220182, 2011). "Furthermore, recent work from our group and others suggests that TLR1-deficiency is clinically relevant with an association in several studies with susceptibility to leprosy and leprosy reversal reaction." (PMID 21852947, 2011). "To date, few pathologies have been genetically associated to TLR2 variants; an increased risk to develop prostate cancer has been traced to TLR1 (and TLR6 and 10 which are located on the same chromosomal locus, and more recently, resistance to leprosy was linked to the frequent I602S TLR1 allele." (PMID 19924287, 2009). "We hypothesized that this TLR1 SNP regulates the innate immune response and susceptibility to leprosy." (PMID 18461142, 2008). "Indeed, certain TLR1 polymorphisms were found more frequently in healthy red squirrels infected with leprosy bacilli compared to diseased animals implying that they may prevent the development of clinical disease." (PMID 30775369, 2019). "A second polymorphism in TLR1, N248S (A743G), is in strong linkage disequilibrium with the TLR1 602I allele which may explain the finding, observed in a Bangladesh cohort of leprosy patients, that M. leprae infection associates with the TLR1 248S/S genotype (OR = 1.34, P = 0.02)." (PMID 22529866, 2012).
leprosy (continued). "To investigate whether TLR1 variation is associated with clinical presentations of leprosy or leprosy immune reactions, we examined 933 Nepalese leprosy patients, including 238 with reversal reaction (RR), an immune reaction characterized by a Th1 T cell cytokine response." (PMID 18461142, 2008). "PB-type leprosy more commonly exhibits TLR1 and TLR2, while MB-type leprosy more commonly exhibits TLR4." (PMID 41239264, 2025). "The evaluated SNVs show that the rs5743618 variant in the TLR1 gene, in combination with the rs5743708 SNV in the TLR2 gene and the rs5743810 SNV in the TLR6 gene, are related with the susceptibility to leprosy in this population." (PMID 37888601, 2023). "A case–control study was conducted in a leprosy endemic region of Colombia (Norte de Santander) to investigate the potential association between single nucleotide variants of the TLR1, TLR2 and TLR6 genes and the development of leprosy." (PMID 37888601, 2023). "Our findings reinforce the idea of the participation of TLR1 and TLR2 polymorphisms in the immune response to leprosy." (PMID 36313452, 2022). "Based on the participation of Toll receptors in modulating the immune response to infection by M. leprae, we suggested that genetic variations in the TLR1, TLR2, and TLR4 genes are somehow associated with leprosy." (PMID 36313452, 2022). "Our observations suggest that TLR1 1805G >T polymorphism showed the presence of the highest frequencies of the G allele in the control group in comparison to the patient group, and this SNP might be associated with resistance against leprosy development in the south Brazilian population." (PMID 36313452, 2022). "On the contrary, in the reaction-free leprosy group, interferon-gamma (IFN-γ) levels were dependent on the association between TLR2 and TLR1 (0.8735)." (PMID 31781675, 2019). "The TLR1 and TLR2 expression levels were compared in all groups showing that these receptors in reaction-free leprosy MB group there were balanced expression (TLR1: 1.01 ± 0.23, TLR2: 1.22 ± 0.18; p = 0.267)." (PMID 31781675, 2019). "In order to verify the association of polymorphisms in TLR1 and NOD2 genes with leprosy a comparison of allele and genotype frequencies was performed." (PMID 30289892, 2018). "Several genes have been associated with leprosy, such as NOD2, PARK2/PARCG, LRRK2, RIPK2, TNF/LTA/HLA, LACC1, IL10, TLR1, and microRNA (miR)-146a." (PMID 29755459, 2018). "A study showed that polymorphisms in the TLR1 gene changed the levels of tumor necrosis factor (TNF) and IL-10 in macrophages and were associated with a higher risk for developing leprosy in India and Brazil." (PMID 30289892, 2018). "The effect sizes of these associations suggest that TLR1 and HLA-DRB1/DQA1 are major susceptibility genes in susceptibility to leprosy." (PMID 20617178, 2010). "Our gene-centric study identified genetic variants at TLR1 and HLA-DRB1/DQA1 as major determinants of leprosy susceptibility." (PMID 20617178, 2010). "In this gene-centric microarray study, we have genotyped SNPs in over 2,000 genes and identified TLR1 and HLA-DRB1/DQA1 as major leprosy susceptibility genes." (PMID 20617178, 2010). "In conclusion, this study suggests that TLR1 and HLA-DRB1/DQA1 are important genetic determinants of susceptibility to leprosy." (PMID 20617178, 2010). "Moreover, the use of molecular methods applied to identify single nucleotide polymorphism (SNP) of Toll-like receptors (TLRs), particularly TLR1, TLR2 and TLR4, have been reported to be associated with distinct leprosy clinical manifestations (19–23." (PMID 37187734, 2023). "Likewise, low TLR1 activity results in lower FNT-α activation, which has been associated with a protective effect against leprosy." (PMID 37888601, 2023).
leprosy (continued). "Also, in the presence of the same TLR1 T allele, when the allele present is the TLR2 T allele, the data suggest protection against the development of leprosy, showing the predominance of the TLR2 polymorphism in the presence of the defective TLR1 allele." (PMID 36313452, 2022). "This study suggests that polymorphisms in TLR1 and TLR2 are factors that may contribute to development/resistance of leprosy." (PMID 36313452, 2022). "Here, we investigated whether SNPs located in eleven genes: CCDC122/LACC1, IFNG, IL6, IL10, IL23R, LRRK2, NOD2, PACRG/PRKN, TLR1, TNF and TYK2 are associated to leprosy susceptibility in a population in the North of Brazil." (PMID 32433683, 2020). "The roles of TLR1 and 2 in leprosy and leprosy reactions were described and it may contribute for perspectives in leprosy management." (PMID 29643852, 2018). "We hypothesize that variants in TLR1 and NOD2 genes increase leprosy susceptibility by alterations in pathogen recognition, signaling and pro-inflammatory molecule coding, although these mechanisms may differ between sexes." (PMID 30289892, 2018). "The markers included 11 SNPs selected to replicate the previously reported associations of the TLR1, NOD2, and IL6 genes and the remaining SNPs in 4 candidate genes TNF, LTA, IFNG, and IL10, in reference to markers previously associated with leprosy per se as an outcome." (PMID 28715406, 2017). "We found no associationbetween markers at TLR1 (rs4833095, namely N248S, and rs5743551) andTLR4 (rs1927914 and rs1927911) and leprosy per seor leprosy reactions in this population (p ˃ 0,05)." (PMID 28327786, 2017). "In addition, genetic polymorphisms in TLR1, TLR2, and TLR4 are associated with leprosy and/or leprosy reactions." (PMID 23350010, 2013). "Subsequently, associations between leprosy and the HLA-DR-DQ region, LACC1, CCDC122, and the I602S functional SNP in the Toll-like receptor 1 (TLR1) gene were replicated in an Indian population and between the HLA-DR-DQ, RIPK2, CCDC122, LACC1, and NOD2 in Vietnam." (PMID 23936864, 2013). "It is conceivable that many of the triacylated lipoproteins displayed by both leprosy and tuberculosis bacilli could signal via TLR1/2 heterodimers and may possess similarly immunosuppressive functions to those of the 19 kDa antigen." (PMID 22529866, 2012). "Here, we investigated the association of single nucleotide polymorphisms (SNPs) in TLR1 (rs4833095) and NOD2 (rs8057341) genes with susceptibility to leprosy and reported the first association between a genetic variant in TLR1 and sex-specific protection against leprosy." (PMID 30289892, 2018). "Whilst most of the genes overlap between the two comparisons, some genes discriminate leprosy patients from HHC exclusively (MBP, MSR1, TLR1, CAMTA, CXCL13 and TFGB)." (PMID 31784594, 2019). "When comparing leprosy patients to HHC, 16 genes showed significantly different expression for leprosy patients (increased: FCGR1A, IL6, IL15, LRKK2, MBP, MSR1, PACRGv1, TLR1, TLR4; decreased: CAMTA, CD3E, CTLA4, CXCL13, GATA3, LAG3, TFGB)." (PMID 31784594, 2019). "Indeed, a strong host genetic contribution to leprosy susceptibility has been well established through the identification of leprosy susceptibility genes by both positional cloning (PARK2, LTA, HLA-C, MRC1) and candidate gene approaches (e.g. TLR1, TNF, CUBN and NEBL)." (PMID 28793313, 2017). "Finally, we showed an unbalance in the expressions of TLR1 and TLR2, in the leprosy reaction groups, in contrast to reaction-free leprosy MB, the group which presented a balance in these expressions." (PMID 31781675, 2019). "Importantly, whilst most of these genes were also differently expressed in leprosy patients compared to EC, MBP, MSR1, TLR1, CAMTA, CXCL13 and TFGB were differentially expressed in leprosy patients exclusively when compared to HHC." (PMID 31784594, 2019).
leprosy (continued). "In addition, lesions from leprosy patients with localized tuberculoid form displayed more strongly expression of TLR2 and TLR1 as compared with the lepromatous form of the disease." (PMID 29643852, 2018). "When analyzing and comparing the expression of TLR1 and TLR2 in the same group, our findings demonstrated differences in these expressions, mainly in the reactional groups, in contrast to the quantitative balance of these receptors in the reaction-free leprosy MB group." (PMID 31781675, 2019).